REN (renin)
Diseases named in the same sentence as REN in open-access papers (continued):
Sharing a sentence is not in itself a finding about the gene and the disease.
liver fibrosis (26 papers, 2012 to 2025). "A study based on a rat model of hepatic fibrosis induced by dimethylnitrosamine (DMN) demonstrated the potential of swertiamarin as a treatment for hepatic fibrosis by targeting the renin-angiotensin system (RAS)." (PMID 40871648, 2025). "The renin–angiotensin–aldosterone system has gained attention due to its role as a mediator of liver fibrosis and hepatic stellate cell (HSC) activation." (PMID 37238965, 2023). "Previous studies have also reported that RAAS inhibitors suppress the progression of liver fibrosis and that direct renin inhibitors and selective aldosterone inhibitors suppress liver fibrosis progression in nonalcoholic steatohepatitis (NASH)." (PMID 36143954, 2022). "Renin–angiotensin–aldosterone activation aggravates liver fibrosis and then aggravates congestion of gastric mucosa." (PMID 36241992, 2022). "Aliskiren has been proven as an effective way to block renin activity and restrain liver fibrosis in experimental models." (PMID 36316746, 2022). "Liver fibrosis development activates the renin-angiotensin system (RAS) and synthesizes angiotensin II26,27." (PMID 36198747, 2022). "Retrospective studies have demonstrated a therapeutic effect of captopril and other inhibitors of the renin–angiotensin system for liver fibrosis and inflammation." (PMID 34535664, 2021). "Countless subsequent proof-of-concept studies confirmed that the renin-angiotensin system significantly contributes to the pathogenesis of hepatic fibrosis." (PMID 26779021, 2015). "Recent research has focused on the renin-angiotensin system as one mechanism of liver fibrosis, in that angiotensin II, the product of this system, has been shown to augment both TGF-β1 and stellate cells directly." (PMID 23193466, 2012). "However, since other clinical trials have not shown clear benefits, more research is needed to confirm the effectiveness of renin–angiotensin system antagonists in treating liver fibrosis." (PMID 41471790, 2025). "These conditions can enhance the renin–angiotensin system and oxidative stress, and might simultaneously affect the development of albuminuria/proteinuria and liver fibrosis." (PMID 37513666, 2023). "The renin-angiotensin system (RAS) plays an important role in hepatic fibrosis." (PMID 23243430, 2012). "Furthermore, activation of the renin-angiotensin system and production of reactive oxygen species due to liver fibrosis may also be involved in DR progression." (PMID 39689076, 2024). "Animal studies fortify these findings with the observed reductions in hepatic steatosis, NAFLD score, liver fibrosis, ALT, SBP, DBP, MAP, renin, and infarct size." (PMID 39275256, 2024). "The animal model suggested that the renin-angiotensin system (RAS), especially angiotensin II (Ang II), played a vital role in activating hepatic stellate cells for liver fibrosis." (PMID 36944947, 2023). "Whether TIIA can improve the liver fibrosis of NASH mice by improving microcirculation, increasing blood flow, and the regulating renin–angiotensin system while improving lipid accumulation is worth further study." (PMID 39334685, 2024).
dementia (25 papers, 2014 to 2025). Loss of intellectual abilities interfering with an individual's social and occupational functions. "Regarding blood pressure-lowering medications, although we found that β-blockers and renin-angiotensin system–acting agents may reduce the risk of dementia, previous publications have been inconsistent." (PMID 39434474, 2024). "This suggests that the renin-angiotensin system may play a role in the pathophysiological processes underlying dementia." (PMID 37568223, 2023). "Therefore, further research is needed on whether an unsuppressed renin level in patients with PA on MRA therapy can serve as a clinical indicator of protection against the elevated risk of developing dementia." (PMID 37568223, 2023). "In this context, the present systematic review seeks to synthesize the current body of evidence addressing the influence of the renin-angiotensin-aldosterone system on dementia and neuropsychiatric outcomes." (PMID 40786281, 2025). "The ACE, REN, APOE, CRP, and IL6 proteins obtained through this bioinformatic approach appear to be associated with both HF and dementia." (PMID 40699836, 2025). "For 2020, the full model included age, gender, Katz index, and qSOFA at hospital admission, dementia, cerebrovascular disease, cancer, and the use of renin-angiotensin system inhibitors." (PMID 36600838, 2023). "The plasma and tissue renin–angiotensin–aldosterone (RAA) system has recently emerged as another risk factor for PD and PD dementia." (PMID 33802165, 2021). "Since most of the identified proteins are not present in both diseases, we performed two independent PPI analyses: the first using the proteins associated with HF (NPPB, REN, ADIPOQ, VWF, ACE, IL6, and CRP) and the second using the proteins involved in dementia (CRP, APP, MAPT, APOE, ACE, and IL6)." (PMID 40699836, 2025). "Besides, some experimental and clinical studies have shown that through inhibiting the renin-angiotensin system in patients with dementia, not only is the progression of renal disease slowed down, but dementia incident risks can also be reduced." (PMID 33028210, 2020). "First, renin–angiotensin–system (RAS) activation may have a role in the formation of dementia." (PMID 28591195, 2017). "The renin-angiotensin system (RAS) is a key player in maintenance of blood pressure, and thus, the RAS is a crucial target for preventing dementia." (PMID 28158298, 2017). "We found that IL6, REN, CRP, and ACE play a role in dementia (purple spheres)." (PMID 40699836, 2025). "We aim to review possible vascular and metabolic factors: Renin-angiotensin-aldosterone system, vascular endothelial growth factor (VEGF), hyperhomocysteinemia (HHcy), as well as the dopaminergic treatment, in the etiopathogenesis of PD dementia." (PMID 33802165, 2021). "We have found that none of the analysed polymorphisms in the genes of renin-angiotensin system, i.e. rs699, rs4762 in AGT, rs5186 in AGTR1, rs5194, rs1403543 in AGTR2 or ACE I/D was associated with MCI or dementia in Parkinson’s disease." (PMID 34302265, 2021).
diabetic cardiomyopathy (25 papers, 2013 to 2025). Diabetic cardiomyopathy is a disorder of the heart muscle in people with diabetes. "Several mechanisms have been implicated in the development of diabetic cardiomyopathy, including upregulated oxidative stress, impaired calcium homeostasis, and activation of the renin-angiotensin system (RAS)." (PMID 24215514, 2013). "The KEGG pathway analysis identified the top 15 factors, including the renin–angiotensin system, pathways involved in cancer, diabetic cardiomyopathy, and the PI3K–Akt signaling pathway." (PMID 39195477, 2024). "In the downregulated DEGs, the enriched pathways were related to pathways of neurodegeneration in multiple diseases, pathways in cancer, microRNAs in cancer, thermogenesis, diabetic cardiomyopathy, and renin secretion." (PMID 39202348, 2024). "In the downregulated DEGs, the enriched pathways were related to pathways of neurodegeneration in multiple diseases, pathways in cancer, thermogenesis, microRNAs in cancer, diabetic cardiomyopathy, and renin secretion." (PMID 39202348, 2024). "The marker genes of pericytes were enriched in renin secretion, vascular smooth muscle contraction, gap junction, purine metabolism, and diabetic cardiomyopathy pathways (p < 0.05)." (PMID 38001896, 2023). "A disintegrin and metalloprotease domain family protein 17 (ADAM17) is a new member of renin-angiotensin system (RAS) but its role in the pathogenesis of diabetic cardiomyopathy (DCM) is obscure." (PMID 36313337, 2022). "In the pathway analysis using the KEGG catalogue, the top 20 pathways associated with renin, aldosterone, and ARR were involved in fatty acid metabolism, diabetes cardiomyopathy, and immunological processes." (PMID 36457109, 2022). "There are several mechanisms involved in the development of diabetic cardiomyopathy, including increased oxidative stress, and activation of the renin-angiotensin system." (PMID 24923878, 2014). "The Rho-associated protein kinase-mediated signaling pathway is known to be involved in the vascular effects of angiotensin II, and renin-angiotensin system blockade is beneficial to the cardiovascular system and a known treatment for diabetic cardiomyopathy." (PMID 24923878, 2014). "Similar hypoxia-induced transcription patterns suggested that the downregulated DEGs and enriched pathways were related to pathways of neurodegeneration in multiple diseases, pathways in cancer, thermogenesis, microRNAs in cancer, diabetic cardiomyopathy, and renin secretion." (PMID 39202348, 2024). "Angiotensinogen, renin, Ang-I and Ang-II are important in diabetic cardiomyopathy." (PMID 23690953, 2013). "Our hypothesis was that in the absence of extracellular ANG II-mediated effects in these animals, development of cardiac dysfunction and prevention of the latter by a renin inhibitor would indicate involvement of intracellular ANG II in diabetic cardiomyopathy." (PMID 24215514, 2013). "The renin-angiotensin-aldosterone system (RAAS) members, especially Ang II and aldosterone, play key roles in the pathogenesis of diabetic cardiomyopathy (DCM)." (PMID 38799171, 2024).
Anxiety (24 papers, 2017 to 2025). Intense feelings of nervousness, tension, or panic often arise in response to interpersonal stresses. "It has been confirmed that anxiety is associated with low‐degree inflammatory response, increased sympathetic nerve activity, and activated neurohormonal pathways involved in atrial remodeling, such as the renin–angiotensin–aldosterone system." (PMID 35043425, 2022). "The potential mechanism for this may be that lack of sleep can activate the hypothalamic-pituitary-adrenal cortex axis and renin-angiotensin system, which are associated with increasing the cortisol and angiotensin II awakening responses, thereby causing anxiety and depressive neurosis." (PMID 38515092, 2024). "The underlying pathomechanism of melatonin’s benefit in anxiety may reside in its sympatholytic action, inhibition of the renin–angiotensin and glucocorticoid system, modulation of GABA–serotonergic signaling and its extraordinary antioxidant and scavenging nature." (PMID 36555831, 2022). "The underlying pathomechanism of melatonin’s benefit in anxiety may reside in its sympatholytic action, interaction with the renin–angiotensin and glucocorticoid systems, modulation of interneuronal signaling and its extraordinary antioxidant and radical scavenging nature." (PMID 36555831, 2022). "This study explores the anxiolytic effects of two ARBs, telmisartan and losartan, by evaluating locomotor activity in Wistar rats, aiming to identify new treatment options for anxiety through modulation of the renin-angiotensin system." (PMID 39429389, 2024). "The mechanism by which anxiety affects blood pressure is complex, including systemic vascular resistance, plasma renin activity, sympathetic activity, and blood lipids in general." (PMID 37456533, 2023). "Two main neuroendocrine systems seem to play a pivotal part in the interaction between BP and anxiety: the hypothalamic–pituitary–adrenocortical axis and the renin–angiotensin system." (PMID 35407607, 2022). "Stress and anxiety do not only increase the workload on the cardiovascular system but also lead to sympathetic activation of the Renin-Angiotensin system." (PMID 36044475, 2022). "Other pathways that increase blood pressure due to anxiety include a change in the systemic vascular resistance, sympathetic activity, plasma renin activity, the homeostasis model and blood lipids." (PMID 32257513, 2020). "As a loss of plasma volume and the resulting increase in sodium concentration reduces the release of aldosterone, it is relevant that the renin-angiotensin-aldosterone system impacts mood and anxiety." (PMID 31450591, 2019). "Furthermore, a significant correlation was observed between the levels of NE, renin, cortisol, and the manifestation of anxiety-like behavior." (PMID 38161999, 2023). "Moreover, anxiety interacts with the renin-angiotensin system, increasing the level of angiotensin II, and some studies show that patients suffering from anxiety exhibit physiological signs of sympathetic activation, as it can strongly stimulate sympathetic nervous outflow and the vasovagal reflex." (PMID 37456533, 2023). "Through shared pathways of inflammatory mediators, reactive oxygen species (ROS), oxidative stress, and renin-angiotensin system (RAS) components, the 14 ppc increase in anxiety is also influencing the forecasted increase in CKD." (PMID 38215160, 2024). "Urinary sodium was reported to be related to salt intake, and high salt intake is reportedly involved in brain renin-angiotensin system activation, not the peripheral system, with resultant increased anxiety, in an animal model." (PMID 29165135, 2017).
Arrhythmia (24 papers, 2011 to 2025). Any cardiac rhythm other than the normal sinus rhythm. "Moreover, the electrical uncoupling caused by the intracellular renin contributes to the impairment of the synchronization of the electrical impulse and consequent generation of cardiac arrhythmias." (PMID 25657639, 2014). "The release of large quantities of renin from hypertrophied myocytes activates the renin–angiotensin system, leading to an influx of calcium ions into myocardial cells through L-type calcium channels, causing intracellular calcium overload and increasing the risk of arrhythmias." (PMID 38460169, 2024). "SRC was proved to be activated in MI models, on the other hand, the inhibitors of SRC reduced the occurrence arrhythmias and sudden cardiac death in mice with a cardiac-specific activated renin-angiotensin system." (PMID 39936089, 2025). "The renin-angiotensin system is involved in the genesis of arrhythmias through its impact on structural and electrical remodeling." (PMID 30534081, 2018). "High short-term coffee intake may dramatically increase plasma renin activity, catecholamine concentrations and blood pressure, increase vascular tension, and induce cardiac arrhythmias." (PMID 39949547, 2025). "Compared with those having acceptable RWA, a lower proportion of patients in the RWA group received diuretic agents and renin–angiotensin–aldosterone system inhibitors while usage of anti-arrhythmia drugs was more frequent in this group, though the difference was not statistically significant." (PMID 36769534, 2023). "A randomized, double-blind, placebo-controlled study showed that excess aldosterone secretion resulted in proarrhythmic effects and moreover confirmed that drugs affecting the renin-angiotensin-aldosterone system (RAAS) were of benefit for arrhythmia and its comorbidities." (PMID 35004871, 2021). "Although evidence shows a close link between arrhythmia and the renin-angiotensin system (RAS), it remains to be determined whether the RAS is involved in the pathogenesis of non-familial SSS." (PMID 22242192, 2012). "Nonetheless, it is hypothesized that the binding of SARS-CoV-2 to the angiotensin-converting enzyme 2 (ACE2) receptor results in activation of the renin-angiotensin pathway which has been implicated in new-onset HTN, acute myocardial injury, cardiac arrhythmias and acute coronary artery events." (PMID 38318191, 2024). "In addition, the release of renin from MCs causes initiation of the local cardiac renin-angiotensin system (RAS), which is responsible for norepinephrine (NE) secretion and results in arrhythmia." (PMID 34512339, 2021).
cardiomyopathy (24 papers, 2014 to 2025). A disease of the heart muscle or myocardium proper. "Studies on the assessment of genetic polymorphisms in genes related to the renin-angiotensin system in relation to cardiomyopathy were included." (PMID 38166133, 2024). "On the other hand, deletion of (P)RR, the gene product of the Atp6ap2 gene, results in a lethal cardiomyopathy phenotype which has been attributed to renin- and prorenin-independent vacuolar H+ATPase and Wnt receptor signaling of this gene." (PMID 24587131, 2014). "In addition, protein digestion and absorption, cell adhesion molecules, cardiomyopathy, renin secretion, and tyrosine metabolism pathways were significantly enriched in the KEGG pathway." (PMID 38172247, 2024). "The etiology of the higher incidence of cardiomyopathy and the lower pulmonary valve flow in the recipient twin compared with the donor twin has been hypothesized as being the result of differing levels of renin–angiotensin activity between the recipient and donor twins." (PMID 35428218, 2022). "These include a high positive selection on KAI14, KIF6 (both indicated in cardiomyopathy), and PDE11A (vasoregulation), as well as pathway enrichments for the renin-angiotensin system and the endothelin-1 pathway, identified in both WedAR and dN/dS analyses." (PMID 35177770, 2022).
hyperlipidemia (23 papers, 2014 to 2025). "To investigate the effects of Ang 1-7 in TAA, we employed a murine model combining two of the major risk factors of TAA, i.e., hyperlipidemia and activation of the renin-angiotensin system leading to hemodynamic abnormalities." (PMID 36555207, 2022). "Possible mechanisms by which MS affects renal physiology include impaired renal hemodynamics, insulin resistance, hyperlipidemia, activation of the renin–angiotensin–aldosterone system, inflammation, and oxidative stress." (PMID 37887410, 2023). "As treatment in this family aims renoprotection, all members with proteinuria are submitted to blockade of the renin angiotensin system, control of blood pressure, and hyperlipidemia, as well as of all metabolic disorders eventually diagnosed." (PMID 33193607, 2020). "The top six pathways for the common downregulated genes between DWC and hyperlipidemia were proximal/distal pattern formation, mineral absorption, renin secretion melanogenesis, phospholipase c-activating G protein-coupled receptor signaling pathway and histone methylation." (PMID 36175575, 2022).